CD4 (CD4 molecule)
Diseases named in the same sentence as CD4 in open-access papers (continued):
Sharing a sentence is not in itself a finding about the gene and the disease.
tumor (continued). "Depletion of CD4+ or CD8a+ T cells by neutralizing antibodies deteriorated the anti-tumor efficacy of the DNA vaccine." (PMID 25013909, 2014). "The CD4+ helper T cells must express thrombospondins in order to contribute to tumor regression following oncogene inactivation." (PMID 25089198, 2014). "After adjustment for age and baseline CD4 count, the probability of tumor improvement was 2.46 times greater (95% CI: 1.57–3.86)." (PMID 24632813, 2014). "Nonetheless, in adjusted analysis accounting for age and baseline CD4 count, those on bleomycin/vincristine were 2.5 times more likely to experience tumor improvement than those on vincristine monotherapy." (PMID 24632813, 2014). "Our results suggest the effect of CR on enhancing anti-tumor responses in aged hosts appears to be due in part to the maintenance of the priming environment during aging, which facilitates CD4 T cell activation in the aged hosts following immune stimulation." (PMID 24682539, 2014). "The sensitization occurred from DNP-modified tumor cell protein from the first injection, inducing cross activation of B- and CD4+ T-cells and subsequent responses against the tumor." (PMID 24949488, 2014). "The data suggest that the Treg within the tumor are more activated than the conventional CD4+ TIL within these progressively growing tumors." (PMID 25436113, 2014). "Dobrzanski summarized recently discovered functions of CD4 T cell and new T cell lineages relevant to tumor immunity and tumor progression." (PMID 25309877, 2014). "Double immunostaining exactly located WSX-1 expression, in the primary tumor and draining lymph nodes, on immune cells endowed with CD11c+ and CD4+ phenotype, to a lesser extent, and rarely on CD8+ phenotype." (PMID 24681516, 2014). "Here, we used the well-established PTLD-SCID mouse model, that permits to assess efficacy of T-cell preparations in a preclinical setting, to comparatively evaluate the tumor-protective potential of different CD4+ T-cell specificities in vivo." (PMID 24853673, 2014). "We believe that the failure is mostly due to the inadequate triggering of the CD4+ T helper (TH) cell arm of the adaptive immunity, as TH cells are necessary to trigger all the immune effector mechanisms required to eliminate tumor cells." (PMID 24600588, 2014). "Compared to baseline, there was increased tumor infiltration following ipilimumab by fully activated (CD69+) CD3+/CD4+ T cells (mean change = 19; SD = 14, p = 0.06) and CD3+/CD8+ T cells (mean change = 11; SD = 19; p = 0.2)." (PMID 24498358, 2014). "In vivo depletions of CD8 and CD4 T cells confirmed that CD8 T cells are required and CD4 T cells are necessary for optimal anti-tumor efficacy." (PMID 25328681, 2014). "Several properties of MTBHsp70 appear in this study to contribute to the generation of tumor-specific CD4+ and CD8+ T-cell immune responses." (PMID 24565018, 2014). "When Id-specific TCR-transgenic mice failed to reject high amounts of injected MHC IINEG MOPC315 cells, CD4+ T cells in peripheral lymphoid organs and in the tumor became deleted." (PMID 24782871, 2014). "Previous studies have shown that docetaxel induced tumor cell death and also increased the number of CD4+ and CD8+ T cells." (PMID 24868562, 2014). "In contrast, tumor protection was impacted in NK and CD4+ T cell-depleted mice, and in IFN-γ-KO and MHC class II-KO mice." (PMID 24830315, 2014). "It has been shown that in vivo specific targeting of tumor antigens to DCs improves the induction of antigen-specific CD4+ and CD8+ T-cell immunity." (PMID 24565018, 2014). "First pre-clinical studies of the combination of these antibodies to achieve blockade of both CTLA-4 and PD-1 showed increased tumor infiltration by CD4+ and CD8+ T-cells, enhanced IFNγ and TNFα production, and reduced amounts of Tregs." (PMID 24822170, 2014).
tumor (continued). "Type-1 CD4+ T (Th1) cells in particular appear crucial for optimal induction, recruitment, and long-term maintenance of therapeutic anti-tumor CD8+ T cells and anti-tumor immunity." (PMID 25325015, 2014). "Tregs are believed to play an important role in down-modulating the function of CD4+ TH cells in adaptive immunity, and their number and function were found to increase in tumor-bearing hosts." (PMID 24600588, 2014). "IL-17A expression was increased not only in tumors, but also in CD4+ T cells isolated from the tumor draining lymph nodes." (PMID 25181290, 2014). "Combination treatment increased proliferation and tumor infiltration by both CD4+ and CD8+ T cells, and intratumor inflammatory cytokine production." (PMID 24855562, 2014). "Adoptive transfer of T antigen-specific CD4+ T cells following sublethal irradiation was more effective in controlling tumor burden and extending survival of tumor-bearing mice than with either modality alone." (PMID 24434638, 2014). "Our results show that the protection from MethA induced tumor growth requires both CD4+ and CD8+ T-cells." (PMID 25340039, 2014). "Promoting CD4+ T helper cell immune responses can be used to enhance the cross-presentation of the tumor antigen following chemotherapy." (PMID 25531529, 2014). "Authors demonstrated that the immunization of mice with flagellin-fused tumor cells induced tumor-specific CD4+ and CD8+ T cell responses and prevented parental tumor growth." (PMID 25071770, 2014). "Tumor lysate-reactive CD4 or CD8 T cell responses were observed in 5 patients, 4 of whom showed decreased frequencies of Tregs and/or MDSCs." (PMID 25694811, 2014). "Very recent work has shown that treating pancreatic tumor-bearing mice with certain compounds, such as Embelin (XIAP inhibitor), can alter the tumor microenvironment by skewing CD4+ T cells away from Th17 differentiation and toward a Th1 phenotype." (PMID 24987392, 2014). "Activated CD4 T cells secrete many cytokines that stimulate dendritic cells, leading to enhanced antigen presentation and potentiated anti-tumor immunity." (PMID 24690990, 2014). "Upon antigen recognition, naïve CD4+ T cells differentiate into Th1 cells and migrate to the tumor." (PMID 24782871, 2014). "Mice treated with cisplatin followed by CpG and PADRE generated the highest percentage of PADRE-specific CD4+ T cells among tumor-infiltrating CD4+ T cells compared to all other treatment groups." (PMID 25531529, 2014). "The requirement of both CD4 and CD8 T cell subsets for CCL21 mediated tumor inhibition was confirmed in CD4 and CD8 T cell knockout mice." (PMID 24810425, 2014). "ERAP1 silencing in T cell lymphoma RMA results in tumor rejection in syngeneic mice by triggering NK cells and subsequently T cell (CD4+ and CD8+) anti-tumor responses." (PMID 25566501, 2014). "In the HCC samples, CD4 and CD8 T cells were observed in the tumor parenchyma and tumor stroma, and the intensity of CD4 or CD8 immunoreactivity was homogeneous in all samples examined." (PMID 25289108, 2014). "It was also observed that CD8+ and CD4+ T-cells as well as Ly6G+ neutrophils were important in mediating the improved anti-tumor efficacy." (PMID 25101247, 2014). "The predominant presence of CD4+ TH2-type cells observed in tumor-bearing hosts before therapy was reconverted in a predominant, although not exclusive, presence of TH1-type cells." (PMID 24600588, 2014). "We unexpectedly found that this anti-TGFβ Ab increased Tregs in the tumor-infiltrating CD4 cells, although the treatment inhibited tumor growth." (PMID 24416401, 2014). "An emphasis is put on T cell receptor (TCR) transgenic models, where anti-tumor responses of naïve CD4+ T cells of defined specificity can be tracked." (PMID 24782871, 2014). "We have demonstrated for the first time that CD4+CD25+ Tregs are systemically increased in response to oral administration of whole (JBS) tumour." (PMID 24832130, 2014).
tumor (continued). "They showed that Hsp70 produced by heated tumour cells activated tumour cells to produce chemokines that increased recruitment of DCs and CD4+ and CD8+ T cells into the tumour and that the recruitment was dependent on TLR4 expressed by tumour cells and DCs." (PMID 25430985, 2014). "CD4+CD25+ Treg cells are augmented in tumor tissue as well as in circulation in patients with malignant melanoma, Hodgkin lymphoma, and lung, gastric, ovarian, pancreatic, and breast cancer." (PMID 24868562, 2014). "The ratio of CD8+ T effector cells to CD4+FoxP3+ Tregs in the tumor environment was shown to be increased." (PMID 25411122, 2014). "On the other hand, several studies have shown that CD4+ T regulatory cells (Tregs) promote tumor progression by inhibiting the functions of CD8+ T cells and natural killer (NK) cells and that the accumulation of Treg cells is associated with a poor prognosis." (PMID 25268644, 2014). "In a model of Id-specific CD4+ T cell responses against an MHC IIPOS B lymphoma, in vitro cytotoxicity was shown to be dependent on signaling mediated by binding of Fas ligand (FasL) on CD4+ T cells to the death receptor Fas on tumor cells." (PMID 24782871, 2014). "Use of TCR-transgenic mice offers the possibility of studying tolerance development by following the fate and function of tumor-reactive CD4+ T cells." (PMID 24782871, 2014). "Here, we review the mechanisms of direct and indirect CD4+ T cell-mediated elimination of tumor cells." (PMID 24782871, 2014). "Mice were depleted of CD4+ T cells in the priming phase and were challenged with TC-1 tumor cells by tail vein injection." (PMID 24594273, 2014). "IL-27 promotes the secretion of IL-10 and IFN- by CD4+ T cells, and we assume that these cytokines have the same effect on tumor rejection as those secreted by CD8+ T cells." (PMID 24633175, 2014). "In the mice injected with PBMCs, numerous CD3+ and CD8+ cells, but less CD4+ cells, were found in spleen and tumor tissues." (PMID 25202383, 2014). "The experiments referred to in the preceding section had features that prohibited detailed studies of the mechanisms of CD4+ T cell-mediated tumor protection." (PMID 24782871, 2014). "Injection of different virus-specific CD4+ T-cell clones showed that single specificities were capable of prolonging mouse survival and that the degree of tumor protection directly correlated with recognition of target cells in vitro." (PMID 24853673, 2014). "To determine how tumor cell USP18 affects these cells and thus the immune response, we injected B16-OVA-GFP or B16-OVA-USP18 tumor cells into C57BL/6 mice that were depleted of CD4+ or CD8+ T cells or NK cells and monitored tumorigenesis." (PMID 24884733, 2014). "Here, we assessed the tumor-protective potential of different CD4+ T-cell specificities in a PTLD-SCID mouse model." (PMID 24853673, 2014). "Tumour growth and survival were monitored, and the role of anti-tumor CD4 and CD8 T cells in therapeutic responses was determined." (PMID 25518732, 2014). "Blood, lymph nodes (LN), spleens (SP), and tumor tissues were harvested at 12 days post T-cell injection, and the transferred human CD4+ T cells were isolated to determine their levels of cAMP, senescence, and suppressive activity." (PMID 25231413, 2014). "Although CTLs are considered to be the main effector cells in anti-tumor immunity, accumulating evidence shows that CD4+ T cells are another critical component." (PMID 24519916, 2014). "Tumor lysate-reactive CD4+ and CD8+ T cell responses in all patients were further investigated in vitro using the IFN-γ secretion assay at different time points after vaccination." (PMID 25694811, 2014). "(ii) CD4+ blasts within the tumor were selectively enriched for cells expressing the Id-specific TCR." (PMID 24782871, 2014). "TGFβ was reported to be responsible for the accumulation of Tregs in tumor by either expanding naturally occurring Tregs or by converting naïve CD4 cells into induced Tregs." (PMID 24416401, 2014).
tumor (continued). "In contrast, the primary activation of naïve tumor-specific CD4+ T cells appears to be similar for the direct and indirect mechanisms, in that presentation of tumor-specific antigen by host APC seems to be required." (PMID 24782871, 2014). "Tregs found at tumor sites contain thymus-derived nTregs and iTregs converted from CD4+CD25- T cells." (PMID 24938080, 2014). "CD4+ T cells either contribute to tumor destruction or facilitate tumorigenesis depending on their phenotype and function." (PMID 25268644, 2014). "The infiltration of highly functional antigen-specific CTLs into the tumor coupled with overcoming the regulatory CD4 T cell environment in the tumor are considered to be key drivers for optimal anti-tumor efficacy." (PMID 25328681, 2014). "Decrease in tumor size was accompanied by lowered number of blood microvessels in the tumor microenvironment and lowered number of regulatory T lymphocytes, as well as by increased levels of CD4+ and CD8+." (PMID 24220932, 2014). "A study of pancreatic cancer patients demonstrated that tumor-produced cytokines (TNF and IL-1β) triggered activation of a Th2 phenotype in cancer-associated fibroblasts, dendritic cells, and naïve CD4+ T cells." (PMID 24672527, 2014). "The deletion of peripheral tumor-specific CD4+ T cells seen in this model for a highly secreted tumor antigen resembles that of exhaustion observed in chronic viral diseases." (PMID 24782871, 2014). "This has been attributed to the rise of HIV/AIDS and the lack of antiretroviral therapy, which has been shown to be crucial for KS tumor regression, decreasing viral loads, and raising CD4 counts." (PMID 24904686, 2014). "We also found that CD4 T cells isolated from both tumor types have an increase in mRNA for IL-6 compared to peripheral blood CD4 T cells." (PMID 25436113, 2014). "In contrast to earlier, but in accordance with recently published data, CD4+ T cells in our LCL-stimulated preparations delayed tumor growth as effectively as the CD8+ components." (PMID 24853673, 2014). "These hypoxia-derived metabolites are potent immunosuppressors that can protect tumor cells from anti-tumor immune responses mediated by tumor-specific CD4+ and CD8+ T cells." (PMID 25231413, 2014). "In contrast, tissues with a high percentage of HLA-DR+ tumor-related macrophages (K3) were characterized by high numbers of CD25+ (CD4+) T cells (E)." (PMID 24797069, 2014). "This indicates that treatment with cisplatin, CpG and PADRE is capable of generating potent PADRE-specific CD4+ T cell responses in TC-1 tumor-bearing mice." (PMID 25531529, 2014). "CD4+ regulatory T cells (Treg) have been shown to limit the development of anti-tumor T cells by killing DCs in tumor-draining lymph nodes (dLN)." (PMID 25349699, 2014). "T regulatory cells (Tregs), a subset of CD4+ cells profoundly influence the immune system in tumor bearing mice, by suppressing both innate and adaptive arms of the immune system." (PMID 25248151, 2014). "The data revealed a significant increase in tumor-infiltrating CD4+ lymphocytes, a trend that was similar for NK, CD19 and CD8+ T cells." (PMID 24466345, 2014). "We also observed a similar Nrp1 expression profile on human tumor infiltrating CD4+ and CD8+ T cells." (PMID 25343644, 2014). "In order to test the immunosuppressive activity of MDSCs by means of an ex vivo analysis, CD4+ or CD8+ lymphocytes isolated from naive C3H mice were cocultured with MDSCs purified from the spleens of tumor-bearing or control mice." (PMID 24738052, 2014). "(iii) Id-specific CD4+ tumor-infiltrating lymphocytes (TIL) were activated (CD69+ CD25+), and proliferated (BrdU+) in clusters associated with MHC IIPOS tumor-infiltrating APC." (PMID 24782871, 2014). "When compared to non-tumor bearing mice, our results show that there is indeed an influx of CD4+ and CD8+ T cells into the brains from the groups in which immunotherapy with 4-1BB activation and CTLA-4 blockade is employed." (PMID 25013914, 2014).
tumor (continued). "Depletion of CD4+ T cells completely abolished the anti-tumor activity of triple therapy (p<0.001) and median survival times were comparable to untreated mice." (PMID 25013914, 2014). "CD4 T cell depletion alone also had an impact on tumor growth and significantly increased the aggressiveness of the tumor model in the absence of PROSTVAC treatment." (PMID 25328681, 2014). "The priming and activation of both CD4 and CD8 T cells have shown to be required for effective OX40-mediated tumor immunity, as depletion of these cells abrogated the regression of tumors; therefore, we assessed both antigen-specific CD4 and CD8 T cells." (PMID 24682539, 2014). "Our assumption is that this treatment interacts on the MDSC/CD4+ T cell interplay and in turn on tumor growth." (PMID 24608924, 2014). "As expected, blockage of gap junction formation with GAP27 also significantly decreased the cAMP levels in naïve CD4+ T cells co-cultured with tumor cells." (PMID 25231413, 2014). "CD4+ T cell-derived IL-4 has been reported to induce granulocyte infiltration, thereby promoting tumor clearance (an action enhanced by IL-13), and conversely increase tumor cells’ resistance to apoptosis by up-regulation of anti-apoptotic proteins." (PMID 25101088, 2014). "We recently reported that tumor resection creates a “window of opportunity” (days 3 to 13 post-resection) with increased frequency of CD4 and CD8 positive activated T cells and decreased tumor-associated immune suppression." (PMID 25432242, 2014). "Dendritic cells isolated from these tumors also potently induced Th2 cytokine secretion from naïve CD4+ T cells in vitro, suggesting that tumor growth is facilitated by a complex network of Th2 paracrine signals." (PMID 24672527, 2014). "The anti-tumor effect was elicited by DC activation and then the infiltration of CD4+ (helper) and CD8a+ (cytotoxic) T cells into tumors." (PMID 25013909, 2014). "Despite this, functional differences between different doses of anti-CD25 Ab were observed in the resulting growth curves, suggesting CD4+CD25+ Treg cells are involved in the T cell response that confers the tumour growth advantage following feeding." (PMID 24832130, 2014). "Despite that, a deal of HA-specific CD4+ T cells kept the functional activity even at the late stage of A20HA tumor growth." (PMID 24693228, 2014). "We previously demonstrated that in the context of a promising immunotherapeutic, OX40 agonist (αOX40), older animals exhibited impaired anti-tumor immune responses and diminished CD4 T cell effector differentiation." (PMID 24682539, 2014). "Tumor growth, as well as levels of natural killer (NK) cells, CD4+ and CD8+ peripheral blood T lymphocyte subpopulations, serum cytokines and vascular endothelial growth factor (VEGF) in tumor tissues were detected." (PMID 24520300, 2014). "PDA patients were divided into two groups based on the median value obtained for either tumor-infiltrating Tregs (17.37% in CD4+ T cells) or tumor-infiltrating CD8+ T cells (28.69% in CD3+ T cells)." (PMID 24637664, 2014). "It was recently shown that B-cells in tumor draining lymph nodes from melanoma patients are responsible for activating a CD4+ T-cell mediated anti-tumor response." (PMID 25380524, 2014). "Having demonstrated that CD8 T cells were essential for effective anti-tumor immunity, we next assessed the immunological effect of CD4 depletion on CD8 T cells." (PMID 25186961, 2014). "Regulatory T cells (Treg) are a subset of CD4+ lymphocytes involved in the maintenance of self-tolerance and the modulation of overall immune responses against infections and tumor cells by controlling CD4+ effector T cells." (PMID 25152827, 2014). "Anakinra was tumoristatic in 7 of 9 tumors resulting in elevated percentages of CD4+ and CD8+ T cells and fewer tumor-associated neutrophils." (PMID 24416335, 2014).